COX5B (cytochrome c oxidase subunit 5B)
Diseases named in the same sentence as COX5B in open-access papers (continued):
Sharing a sentence is not in itself a finding about the gene and the disease.
atherosclerosis (1 paper, 2022). A disease characterized by the build-up of fatty material and calcium deposition in the arterial wall resulting in partial or complete occlusion of the arterial lumen. "Moreover, Pcb3, Cox5b, and Myl4 are involved in atherosclerosis, diabetic cardiomyopathy, and cardiac muscle contraction, respectively." (PMID 35479750, 2022).
breast tumor (1 paper, 2015). "By performing stable isotope labeling with amino acids in cell culture (SILAC) in the normal epithelial cell line (16N) and primary breast tumor cell line (NT), we obtained many candidate genes, of which COX5B was increased in NT compared with 16N." (PMID 26506233, 2015).
cryptorchidism (1 paper, 2024). The failure of one or both testes of a male fetus to descend from the abdomen into the scrotum during the late part of pregnancy. "It suggests that cryptorchidism indeed impairs mitochondrial function in Leydig cells by affecting the expression of COX5B, leading to diminished fertility." (PMID 39586785, 2024). "Data analysis of cryptorchidism‐related datasets in the GEO database and gene sequencing results from our institution, along with bioinformatic analysis of the merged mitochondrial gene datasets, revealed that COX5B is differentially expressed in the testes of children with cryptorchidism." (PMID 39586785, 2024). "To this end, we investigated the aberrant low expression of COX5B in a rat model of cryptorchidism, and subsequently low expression of COX5B in Leydig cells was observed to decrease cell proliferation and increase apoptosis, and impaired the metabolic function of mitochondria." (PMID 39586785, 2024).
cyst (1 paper, 2020). A sac-like closed membranous structure that may be empty or contain fluid or amorphous material. "Therefore, the downregulation of COX5B expression suggests that mitochondrial energy supply was weakened during the cyst formation, and coordination of the cysts into a low-energy metabolic state was conducive to survival in adversity." (PMID 32225121, 2020). "It is therefore indicated that downregulating COX5B might have a role in inhibiting the cell growth and promote the cyst formation of P. cristata." (PMID 32225121, 2020).
dilated cardiomyopathy (1 paper, 2023). Cardiomyopathy which is characterized by dilation and contractile dysfunction of the left and right ventricles. "We quantified COX5A, COX5B, and SOD2 protein levels in heart samples from patients with end-stage dilated cardiomyopathy (DCM) or subjects without obvious cardiovascular diseases, and observed that COX5A and SOD2 were clearly down-regulated in heart tissues with DCM." (PMID 37373547, 2023).
heart failure (1 paper, 2025). Inability of the heart to pump blood at an adequate rate to meet tissue metabolic requirements. "We found that the pairs Uqcrb and Coxcb, and Atp5pf and Cox5b, reported as simultaneously upregulated in paradoxical low transvalvular flow and low gradient patients who develop advanced heart failure symptoms, are synergistically expressed in normal conditions." (PMID 41296444, 2025).
lung squamous cell carcinoma (1 paper, 2025). "Three compounds (gallic acid, betulinic acid, and caffeic acid) had a significant inhibitory effect on lung squamous cell carcinoma via five biolabels (CPS1, CKM, CPT1B, COX5B, and COX4I1)." (PMID 41502520, 2025).
lymph node metastasis (1 paper, 2025). "In summary, these results indicate that COX5B is highly expressed in LUAD, is closely associated with lymph node metastasis, T stage, and clinicopathological stage, and serves as an independent prognostic marker for LUAD." (PMID 41502520, 2025). "COX5B expression was significantly related to lymph node metastasis, pathological T stage, and clinicopathological stage." (PMID 41502520, 2025).
mental disorder (1 paper, 2020). A disease that has its basis in the disruption of mental process. "Three (COX5B, SEC62, and NDUFA2) were validated with another technique and were also differentially regulated in postmortem brain of subjects with mental disorders." (PMID 32184383, 2020).
multiple myeloma (1 paper, 2022). "Our results indicate that NDUFB8, NDUFA6, COX6C, COX5B, and USMG5 might influence the immune microenvironment of multiple myeloma patients, as well as the response to treatment and prognosis of patients with this disease." (PMID 36551283, 2022).
myocarditis (1 paper, 2024). Myocarditis is a condition that is characterized by inflammation of the heart muscle (myocardium). "Cox5b (p = 0.049) was the sole significantly bound nuclear encoded mitochondrial ETC region from complex IV, and in complex V (i.e., the ATP synthase) Atp5e (p = 0.018), Atp5g1 (p = 0.044), Atp5k (p = 0.031), and Atp5l (p = 0.037) bound more in females with myocarditis compared to males." (PMID 39696682, 2024).
oral cancer (1 paper, 2016). "Therefore, we suggest that the low expressions of Cox5b and Uqcrh in fenofibrate-treated cells are likely to contribute a significant impact to regulating ROS production involved in oral cancer development." (PMID 26869356, 2016).
small cell lung carcinoma (1 paper, 2024). Small cell lung cancer (SCLC) is a highly aggressive malignant neoplasm, accounting for 10-15% of lung cancer cases, characterized byrapid growth, and early metastasis. "MA treatment of small cell lung carcinoma DMS114 cells caused downregulation of glycolytic proteins (ALDOA, GAPDH, ENO1, PyKM2 and LDHA) as well as upregulation of OxPhos proteins (cytochrome b-c1 complex subunit 2 and cytochrome c oxidase subunit 5B)." (PMID 39288141, 2024).
testicular disease (1 paper, 2024). "The analysis shows that COX5B is highly expressed in the testis and has the highest correlation with testicular disease." (PMID 39586785, 2024).
virus infection (1 paper, 2012). "Given that the productions of IFNs are important for the host to fight against viruses, we first assessed whether endogenous COX5B is involved in induction of IFN-β production upon virus infection." (PMID 23308066, 2012).
tumor (18 papers, 2012 to 2025). "Some interesting genes were identified as correlation-enhancing genes—PKM: pyruvate kinase and repressing genes; COX5B: cytochrome c oxidase subunit 5B in rS-pS —indicating a possibility of alterations of mRNA-to-protein correlation of the energy metabolism–associated genes in the tumor." (PMID 33384992, 2020). "In addition, COX5B is also associated with tumor proliferation." (PMID 28628609, 2017). "Subsequent investigations demonstrated that berberine effectively targeted COX5B, diminishing its protein expression and consequently inhibiting cell proliferation and tumor growth in LUAD." (PMID 41502520, 2025). "Recently, growing studies have suggested that COX5B influences tumor development through the regulation of mitochondrial function." (PMID 41502520, 2025). "In vivo studies using subcutaneous xenograft models confirmed that MZT2B knockdown markedly impaired NSCLC tumor growth, reduced proliferation, increased apoptosis, downregulated COX5B expression and diminished mitochondrial function." (PMID 41213905, 2025). "MZT2B critically drives NSCLC cell proliferation, survival, migration, and tumor growth possibly by maintaining mitochondrial function and respiration, potentially through the regulation of COX5B." (PMID 41213905, 2025). "Specifically, immunohistochemistry (IHC) assays revealed a 2.32-fold increase of COX5B in tumor tissues compared to that in adjacent normal tissues (p = 0.0044)." (PMID 41502520, 2025). "Nonetheless, the dramatic reduction of tumor growth due to knockdown of blw, COX5B, or RFeSP definitely confirmed the critical need for mitochondrial respiratory fluxes." (PMID 40822358, 2025). "In the following study, it is essential to construct an orthotopic tumor model with COX5B-knockdown and control LUAD cells to analyze the differences in immune cell infiltration using flow cytometry or single-cell sequencing." (PMID 41502520, 2025). "Conversely, the suppression of COX5B expression has been found to impede cancer cell growth by dampening mitochondrial activity, thereby curbing tumour progression." (PMID 39586785, 2024). "In HNSCC, COX5B was reported as a potent tumor-suppressive gene, whereas in almost all other cancer types, this protein exhibited a growth-promoting property, and its higher levels were correlated with unfavorable clinical outcomes." (PMID 35052740, 2021). "In our study, we further validated that COX5B expression was higher in primary tumor tissues and metastatic lymph nodes than in normal tissue." (PMID 26506233, 2015). "This study established that upregulated COX5B was positive associated with poor patient prognosis in LUAD, elucidating the mechanisms by which berberine targets COX5B to inhibit tumor growth, thereby providing a novel therapeutic target and strategy for the clinical management of LUAD." (PMID 41502520, 2025). "Knockdown DARS2 and COX5B inhibited tumor cell proliferation." (PMID 41502520, 2025). "Berberine suppressed COX5B and reduced tumor proliferation via IHC assays." (PMID 41502520, 2025). "It was suggested that the level of COX5B protein may be related to the tumor size;also, its up-regulated form showed a worse disease free-survival." (PMID 40636894, 2023). "A higher COX5B tumor/nontumor expression ratio was associated with unfavorable clinical outcomes (p = 0.001 and 0.011 for overall and disease-free survival, respectively." (PMID 35052740, 2021). "In multivariate analysis, the COX5B level (p = 0.004), gender (p = 0.023), age (p = 0.011), height (p = 0.023), tumor differentiation status (p = 0.005), adjuvant chemotherapy received (p = 0.011), and OCR T/N ratio (p < 0.001) remained as potential predictors of DFS." (PMID 35052740, 2021). "The loss of COX5B-mediated facilitation of bioenergy production resulted in AMPK activation, leading to repression of UHMK1 (an oncogene) expression and induction of ULK1 (a tumor suppressor) via unidentified mechanisms." (PMID 32580279, 2020).
tumor (continued). "Furthermore, COX5B expression was examined in 40 tumor tissue and 20 normal or benign tissue samples." (PMID 26506233, 2015). "Patients with COX5B T/N ≥ 1 had greater height (p = 0.021), tumors located within the proximal colon (p = 0.007), tumors with good differentiation (p = 0.016), a shorter distance from the tumor to the serosa (p = 0.048), and a higher oxygen consumption rate OCR T/N ratio (p = 0.027)." (PMID 35052740, 2021). "Berberine targets COX5B to inhibit the proliferation of LUAD cells in vitro and tumor growth in vivo." (PMID 41502520, 2025). "OGDH subunit E2, namely dihydrolipoyllysine-residue succinyltransferase (DLST), cytochrome c oxidase subunit 5B (Complex IV), and persulfide dioxygenase ETHE1 were less-abundant proteins in D tumor samples." (PMID 39195201, 2024).
cancer (13 papers, 2015 to 2025). A tumor composed of atypical neoplastic, often pleomorphic cells that invade other tissues. "Recently, COX subunit 5B (COX5B) emerged as a potential biomarker associated with unfavorable prognosis by modulating cell behaviors in specific cancer types." (PMID 35052740, 2021). "Overexpression of COX5B is associated with a poor prognosis in many cancers." (PMID 34439877, 2021). "Loss of COX5B could inhibit cancer cell proliferation and lead to mitochondrial dysfunction." (PMID 26506233, 2015). "This suggests that MZT2B promotes NSCLC malignancy, at least in part, by orchestrating mitochondrial function through its regulation of COX5B, thereby supporting the heightened metabolic demands of cancer cells." (PMID 41213905, 2025). "From TCGA database, Kaplan-Meier analysis noted that COX5B was correlated with overall survival, progression-free interval, and disease-specific survival in several cancers." (PMID 41502520, 2025). "This evidence suggested that COX5B exerts a cancer-promoting role in CRCs, albeit its molecular mechanisms in modulating CRCs growth and susceptibility to anticancer drugs requires further investigation." (PMID 35052740, 2021). "Except for HNSCC, the role of COX5B in almost all other types of cancers exhibited as growth-promoting property as higher levels of COX5B correlated with unfavorable clinical outcomes, similar to what was found in this study." (PMID 32580279, 2020). "To discover the expression pattern of COX5B across various cancers, we searched the TCGA database." (PMID 41502520, 2025). "Within the enzymes of mitochondrial metabolism involved in cancer progression, besides isocitrate dehydrogenase and malate dehydrogenase, subunits of the cytochrome c oxidase (complex IV of the respiratory chain) such as COX5B have also been reported." (PMID 37297007, 2023). "Additionally, the correlation between COX5B expression and bioenergetic alterations could be traced to as early as the origin of the adenomatous–carcinoma sequence in the adenomatous polyps." (PMID 35052740, 2021). "The COX5B gene is highly expressed in HCC, thus, confirming its putative role as a growth-promoting agent in this type of cancer." (PMID 37894381, 2023). "However, the molecular mechanisms of COX5B in modulating cancer growth remained largely unknown." (PMID 32580279, 2020). "Additionally, COX5B and MS4A1 were notable for their prognostic relevance across three cancer types." (PMID 40396172, 2025). "Here, we found the effect of gastrin on the expression levels of COX17, COX5B, and ATP5J proteins that are involved in the mitochondrial respiratory chain, which may reveal one of the important mechanisms of gastrin as a cancer promoting factor." (PMID 33937399, 2021). "Therefore, COX5B might function as a critical metabolic switch to influence the energy balance between OXPHOS and glycolysis in cancer cells." (PMID 41502520, 2025).
infection (4 papers, 2012 to 2022). The state of being infected such as from the introduction of a foreign agent such as serum, vaccine, antigenic substance or organism. "At 6 h post infection, the energy metabolism related genes (ATP5G2, COX17, COX5B, GSTP1, NDUFAB1 and NDUFS2) were suppressed." (PMID 23527143, 2013). "Furthermore, we also found that COX-5B was significantly up-regulated, while TRIM25, TRIM21, TRIM27 and TRIM26 were significantly down-regulated in the PAMs with a PRRSV-ADE infection in this study." (PMID 36680075, 2022). "Furthermore, the expression of several innate immune response regulators (COX-5B, MMP-9, TRIM21, TRIM25 and TRIM26) in the PAMs were also regulated differently during the PRRSV-ADE infection." (PMID 36680075, 2022).
metabolic disorders (1 paper, 2015). "Considering the role COX5B in mitochondrial electron transport chain, COX5B knockdown may be associated with mitochondrial dysfunction and metabolic disorder." (PMID 26506233, 2015). "What's more, silence of COX5B leads to metabolic disorders, such as increased glucose uptake and decreased lactate secretion." (PMID 26506233, 2015).
COX5B also shares sentences with these, for which no sentence is quoted: Huntington disease (4 papers); Alzheimer disease (3); cardiovascular diseases (3); neurodegenerative disease (3); brain disease (2); glioma (2); head and neck squamous cell carcinoma (2); lung adenocarcinoma (2); Atrophy (1); bladder urothelial carcinoma (1); breast invasive carcinoma (1); cervical squamous cell carcinoma (1); cholangiocarcinoma (1); colon cancer (1); cutaneous squamous cell carcinoma (1); diabetes (1); diabetic cardiomyopathy (1); endocervical adenocarcinoma (1); endometrial cancer (1); glioblastoma (1); head and neck cancer (1); Hepatic fibrosis (1); legionellosis (1); liver cancer (1); lung carcinoma (1); melanoma (1); multiple sclerosis (1); neurological diseases (1); pancreatic adenocarcinoma (1); prostate adenocarcinoma (1).
A further 3 diseases each share a sentence with COX5B in 1 paper.